IGF2 (insulin like growth factor 2)
Diseases named in the same sentence as IGF2 in open-access papers (continued):
Sharing a sentence is not in itself a finding about the gene and the disease.
tumor (continued). "Furthermore, our results show that miR483-5p, but not miR483-3p, enhances Igf2 expression in mouse C2C12 cells, and this is consistent with the original report of this mechanism using human tumor cells." (PMID 34593874, 2021). "There were four possible patterns of allelic IGF2 expression in tumor tissue compared to matched adjacent normal mucosa: maintenance of imprinting (MOI) in both tissues, LOI in both tissues, LOI in tumor and MOI in normal mucosa, and MOI in tumor and LOI in normal mucosa." (PMID 30509319, 2018). "In addition, IGF2 LOI is observed in non-neoplastic kidney parenchyma and frequently in early-stage tumours, indicating the importance of IGF2 in Wilms' tumorigenesis." (PMID 16909133, 2006). "It is likely that a suite of biomarkers, both in the host and tumor will be required rather than single biomarker selection, with some candidates for study in RMS including IGF2, pIGF1R/IGF1R, IGF1, pIRS-1/IRS-1, pIR-A/IR-A, IGFBP-6, and maybe others such as HSPs, PDGFR and Erb2." (PMID 21437217, 2011). "Furthermore, the overlap of EGF and IGF-2 pathways, as demonstrated by merging both networks into a single pathway, could enable IGF-2 to take over the functional role of EGF and thus render the tumor cell independent of EGF signaling." (PMID 21464922, 2011).
cancer (596 papers, 1997 to 2026). A tumor composed of atypical neoplastic, often pleomorphic cells that invade other tissues. "The stemness of cancer cells is primarily driven by IGF2 signaling, which causes the formation of pre-metastatic niches." (PMID 41007637, 2025). "Insulin-like growth factor-binding protein 2 (IGFBP-2), which binds IGF-2, is linked to cancer metastasis through its interaction with HSP27." (PMID 40806747, 2025). "PLAG1 stimulates the IGF2 gene and excess production of IGF2 is considered one mechanism linked to tumors and cancers." (PMID 38586898, 2024). "Hallmark Kras Signaling UP and Hallmark KRAS Signaling DN (Overlap Genes including PTGS2, IGF2): KRAS signaling is pivotal in many cancers, affecting cell growth, apoptosis, and migration." (PMID 39000413, 2024). "IGF1 is associated with an increased risk of colorectal, prostate, breast, and lung cancers, while IGF2 is implicated in colorectal cancer, liver cancer, and prostate cancer." (PMID 38339282, 2024). "The insulin-like growth factor 1 receptor (IGF-1R) and its ligands (IGF-1 and IGF-2) are essential for cell, organ, and organismal growth, and are linked to cancer risk, cancer progression, and inflammation." (PMID 39608716, 2024). "Juxtanuclear granular expression of IGF-2 was considered a distinctive diagnostic marker for carcinomas in this study." (PMID 38802933, 2024). "The involvement of IGF2 in carcinogenesis depends on its ability to link high energy intake, increase cell proliferation, and suppress apoptosis to cancer risk, and this is likely the key mechanism bridging insulin resistance to cancer." (PMID 36672737, 2023). "This is important given that their methylation status plays a direct role in the transcriptional activation of the underlying IGF2 promoters in cancer." (PMID 37371750, 2023). "Several studies have shown that both autocrine and paracrine IGF2 are associated with drug resistance in various cancer models and that targeting the IGF signaling pathway can sensitize cancer cells to therapy." (PMID 36672737, 2023). "As reviewed by Callum Livingstone, the expression of IGF2 is associated with the development of various cancers." (PMID 36246634, 2022). "In contrast, the nearby paternally-expressed IGF2 gene that encodes insulin-like growth factor 2 is involved in fetoplacental development and growth and has been implicated in both cancer and cardiovascular disease." (PMID 36142363, 2022). "Elevated serum IGF2 is associated with an increased risk of developing various cancers, including colorectal." (PMID 34100888, 2021). "Even though the role of IGF-2 in cancer is controversial, some studies demonstrate a clear correlation of its overexpression with the risk of some cancer development." (PMID 34069554, 2021). "Numerous in vitro and clinical studies have disclosed that increased IGF-2 activity is implicated in cancer cell proliferation, migration, and invasion." (PMID 34203267, 2021). "Although the loss of imprinting regulation in cancer is believed to occur as a consequence of the hypermethylation of IGF2/H19lnc cluster, in HCC the cluster is hypomethylated." (PMID 34062786, 2021). "IGF2 encodes a member of the insulin family of polypeptide growth factors, which are involved in development, cancer biology and growth." (PMID 35095996, 2021). "In human HCC, overexpression of IGF2 is associated with fetal malformations and a variety of cancers." (PMID 34200243, 2021). "High levels of IGF-1 and IGF-2 are linked to the growth of cancer or with cancer recurrence in cancer survivors." (PMID 32399389, 2020). "Insulin-like growth factor-2 messenger RNA-binding protein 3 (IGF2BP3 or IMP3) is an oncofetal protein that is expressed in various cancer types, and its expression is often associated with poor prognosis." (PMID 32293476, 2020). "The H19/IGF2:IG-DMR hypermethylation, for example, is coupled to the loss of imprinting of IGF2 and H19 in several congenital diseases and cancers, including WTs." (PMID 33217932, 2020).
cancer (continued). "Genetic mutations in IGF2R can modify the bioavailability of IGF2 so that cancer cells can dramatically proliferate." (PMID 32075092, 2020). "BWS is less frequently caused by activation of IGF2 and reduced H19 expression, although in these cases it is often accompanied by Wilms’s tumors and other cancers." (PMID 31143763, 2019). "For examples, increased activity of IGF2 has been associated with many types of cancer, and upregulated expression of its intronic miR-483-3p protects cells from apoptosis." (PMID 31464655, 2019). "One such example is IGF2, a promoter of proliferation that is associated with many types of cancer and with the overgrowth phenotype observed in Beckwith–Wiedemann syndrome." (PMID 31143763, 2019). "Loss of imprinting was a well-known mechanism of IGF2 whose expression is also rising in a variety of cancer cells." (PMID 30787268, 2019). "Along with Wilms’ tumor, LOI of the IGF2 gene is associated with many other types of cancer, including lung, colon, pancreatic, cardiac, hepatic, and ovarian tumors." (PMID 31143763, 2019). "The congenital overgrowth disorder, Beckwith–Wiedemann syndrome, is associated with increased cancer risk and is frequently associated with disrupted imprinting of the IGF2 gene." (PMID 31179642, 2019). "Elevated serum IGF2 was proven to be associated with increased risk of developing various cancers including colorectal, prostate and lung." (PMID 31133028, 2019). "It is today recognized that the IR is overexpressed in many tumors and that also IGF-2 and IR-A overexpression is present in a wide range of human cancers and is associated with a poor prognosis." (PMID 30453495, 2018). "IGF-2 works as a growth factor; thus, in addition to cell survival, overexpression of IGF-2 can cause an increase in cancer cells." (PMID 34466449, 2018). "LOI of IGF2 in colon mucosa has been associated with an increased cancer risk by enhancing stemness, self‐renewal, and resistance against chemo‐ and radiotherapy." (PMID 29239100, 2018). "Human cancer cells often exhibit impaired IGF2 expression and the underlying mechanisms are multifaceted and complex." (PMID 29017567, 2017). "Elevated serum IGF2 is also associated with increased risk of developing various cancers including colorectal, breast, ovarian, testicular, liver, and resistance to anticancer regimens." (PMID 28521298, 2017). "For example, IMP2 binds to the mRNA that encodes the protein IGF2, which is a protein that helps cells to grow and is commonly produced in large quantities by cancer cells." (PMID 28753127, 2017). "IGF2 is the predominant IGF in adult humans, and IGF2 abnormalities have been associated with a variety of tumors and overexpression of IGF2 is closely related to worse prognosis in cancer." (PMID 27895308, 2016). "Loss of IGF2 or H19 imprinting leads to IGF2 upregulation and subsequent H19 promoter hypermethylation, a phenomenon commonly found in cancers." (PMID 26989421, 2016). "In cancer, loss of imprinting has been largely reported, insulin-like growth factor 2 (IGF2) being the most studied locus." (PMID 25755686, 2015). "Among p62/IMP2 target mRNAs, most are associated with cancer progression, such as IGF2 mRNA and c-myc mRNA." (PMID 26416451, 2015). "Extensive in vitro and in vivo studies have implicated IGF-1R, IGF-1, and IGF-2 signaling in cancer development, progression, and maintenance." (PMID 25424625, 2014). "More important, in mouse myoblasts, 91H was determined to be implicated in co-regulation of genes at the H19/IGF2 locus contributing to carcinogenesis and cancer progression." (PMID 25058480, 2014). "We also observed a substantial alteration in chromatin structure within human cancers that have lost IGF2 imprinting, resulting in a striking loss of long-range interactions across the IGF2/H19 locus." (PMID 24019942, 2013).
cancer (continued). "We have previously shown that loss of IGF2 imprinting in cancer is accompanied by loss of normal long-range intrachromosomal interactions involving the IGF2/H19 locus." (PMID 24019942, 2013). "Loss of (genomic) imprinting (LOI) of the insulin-like growth factor 2 gene (IGF2) is a common epigenetic abnormality in many human cancers." (PMID 23900345, 2013). "Lower levels of IGF2 methylation have been related to increased cancer risk and IGF2 methylation in this study was associated with a significantly lower placental weight and a borderline significant reduction in birth weight." (PMID 23922667, 2013). "As regards IGF2, dysregulation has been suggested to be an early change in PCa, and inactivation has been associated with cancer progression." (PMID 23135352, 2013). "IGF2 encodes the mitogenic anti-apoptotic peptide IGF-II that is overexpressed in several human cancers cells." (PMID 23171475, 2012). "In our previous study, we found that loss of IGF2 imprinting is present in both colorectal tissues and cancer cell lines (HCT-8, HT-29, HCT15, and SW1222)." (PMID 23171475, 2012). "The overexpression of insulin-like growth factor 2 (IGF2) and loss of IGF2 imprinting occurs in diverse cancers, further suggesting a role for this pathway in carcinogenesis." (PMID 21437228, 2011). "Aberrant DNA methylation at the IGF2 and neighboring H19 DMRs has been associated with deregulated IGF2 expression, childhood cancers and several chronic diseases during adulthood." (PMID 22414206, 2011). "Methylation profiles of the IGF2-H19 locus in many cancers indicate that loss of IGF2 imprinting and methylation are often disconnected during neoplasia." (PMID 19956766, 2009). "IGF2 and H19 are closely linked and reciprocally imprinted, and epigenetic alterations in human cancers at an intergenic differentially methylated region (DMR) are associated with LOI of IGF2 and silencing at H19." (PMID 15798773, 2005). "Tumors based on other WT genes or general cancer predisposition mutations and IGF2 imprinting defects were histologically more diverse: stromal or epithelial histology was rare, but triphasic or regressive tumors were frequent (43%) and there was a high rate of high-risk histology (21%)." (PMID 40340749, 2025). "In particular, tirzepatide may increase the synthesis of insulin, IGF-1, IGF-2, and their binding proteins—factors that have been linked to elevated cancer risk, especially in patients with prior pancreatic injury." (PMID 41310711, 2025). "Other factors, such as IGF2 imprinting and antivascular endothelial growth factor therapy by induction of the microseminoprotein, prostate-associated protein, are also critical in cancer development." (PMID 38791215, 2024). "Cancer-associated fibroblasts (CAF) from invasive tumors secrete IGF2, which is due to the release of β fibroblast growth factor (βFGF) and transforming growth factor β (TGFβ) from epithelial tumor cells resulting in fibroblasts activation caused by the release of βFGF and TGFβ." (PMID 38887298, 2024). "Nonetheless, the mechanistic relationship between promoter usage, both under monoallelic (under maintenance of imprinting, MOI) and biallelic status (caused by LOI), and the observed total IGF2 expression pattern/levels in cancer remains an active area of investigation." (PMID 37371750, 2023). "In detail, it has been demonstrated that IGF-1R signaling can contribute to malignant transformation and cancer growth and that the upregulation of IGF-1R and IGF-2 as well as the deregulation of their downstream signaling molecules increase the risk of cancer development and invasiveness." (PMID 36902237, 2023). "Autocrine IGF2 is also implicated in cancer resistance to IGF1R blockade." (PMID 36672737, 2023). "Another potential risk of therapeutic IGF2 is increased cancer incidence." (PMID 36971212, 2023). "In addition, there are reports on miR-483-5p indicating associations with 483-3p, the IGF2 gene, cancer, and adipogenesis in physical diseases." (PMID 35409234, 2022).
cancer (continued). "Overexpression of IGF2 is frequent in human cancers and is associated with a poor prognosis." (PMID 35974000, 2022). "Furthermore, in our study the mRNA level of the LGR5 transcript variants were positively correlated with the mRNA level of CTGF, P4HA1, and IGF2, as all of these genes are linked to metastasis in cancer." (PMID 30770730, 2019). "IGF2 is overexpressed in a spectrum of human cancers, and is associated with a poor prognosis." (PMID 28521298, 2017). "Notably, IMP2 deletion from the human cancer cells causes a much greater decrease in IGF2 production than in MEFs, ranging from ~35–50% of parental levels." (PMID 28753127, 2017). "This could have potentially provided escape mechanisms for insulin and IGF-2 signaling that have been implicated in cancer cell progression, leading to limited clinical response." (PMID 27127884, 2016). "The loss of imprinting (LOI) of IGF2 has been associated with the development of cancer." (PMID 25364428, 2014). "Notably, LOI at IGF2 is more extensive in men with associated cancer supporting a role in cancer promotion with aging." (PMID 24558376, 2014). "Loss of imprinting leads to overexpression of IGF-2 and occurs frequently in human cancers." (PMID 23983688, 2013). "In cells that express both parental IGF2 alleles, the increase in IGF2 production may be a mechanism for promoting cancer development." (PMID 24066089, 2013). "Increased activity of the IGF2 gene has been associated with many types of cancer." (PMID 23386832, 2013). "Loss of imprinting of the Igf2 gene is one of the most common observations in cancers." (PMID 21464922, 2011). "In murine cancer models methylation changes in the differentially methylated region 2 of IGF2 have been associated with overexpression of IGF2, which in turn might activate IGF1R signalling and increase cell growth." (PMID 20338046, 2010). "Although the mechanisms underlying IGF2 LOI in human cancer remains unknown, it is likely to directly or indirectly involve the H19 ICR." (PMID 19737423, 2009). "Whilst these discrepancies might be attributed to low power in the paternal analysis (only available in Sweden), this might also suggest that maternal effects involved in the control of fetal growth (including IGF-2 gene expression) also play a role in subsequent offspring cancer risk." (PMID 41146054, 2025). "Accordingly, the present review on human IGF2 gene regulation focuses, specifically, on integrating the current understanding of IGF2 gene epigenetic control with the underlying mechanisms occurring at its promoter and transcript (mRNA) levels in cancer and IGF2-expression syndromes." (PMID 37371750, 2023). "The increased expression of MEK and phosphorylated ERK and the concomitant decrease in IGF2 and IGF-1R expression in co-culture conditions might also indicate a shift from the endogenous paracrine IGF2 axis towards a cancer promoting ASC-associated leptin axis." (PMID 31817072, 2019). "Moreover, the association of IGF2R/IGF2 with cancer progression appears controversial." (PMID 30168002, 2018). "In addition, IGF-2 is a well-described transforming growth factor whose elevated expression as a result of loss of imprinting can be found in a considerable percentage of human cancers." (PMID 23383308, 2013). "Moreover LOI of IGF2 might provide a marker for identifying an important subset of the population with cancer or at risk of developing cancer." (PMID 19737423, 2009). "Pan-cancer transcriptomic analysis of The Cancer Genome Atlas (TCGA) demonstrated that PPGL overexpresses IGF2, with pseudohypoxic tumors exhibiting higher expression compared to other molecular clusters." (PMID 42113881, 2026). "IGF2 is a single-chain polypeptide belonging to the insulin-related protein family, serves as a critical regulator of development and cancers 64-66." (PMID 41424856, 2026).